PER2 (period circadian regulator 2)
Description:
Transcriptional repressor which forms a core component of the circadian clock. The circadian clock, an internal time-keeping system, regulates various physiological processes through the generation of approximately 24 hour circadian rhythms in gene expression, which are translated into rhythms in metabolism and behavior. It is derived from the Latin roots 'circa' (about) and 'diem' (day) and acts as an important regulator of a wide array of physiological functions including metabolism, sleep, body temperature, blood pressure, endocrine, immune, cardiovascular, and renal function. Consists of two major components: the central clock, residing in the suprachiasmatic nucleus (SCN) of the brain, and the peripheral clocks that are present in nearly every tissue and organ system. Both the central and peripheral clocks can be reset by environmental cues, also known as Zeitgebers (German for 'timegivers'). The predominant Zeitgeber for the central clock is light, which is sensed by retina and signals directly to the SCN. The central clock entrains the peripheral clocks through neuronal and hormonal signals, body temperature and feeding-related cues, aligning all clocks with the external light/dark cycle. Circadian rhythms allow an organism to achieve temporal homeostasis with its environment at the molecular level by regulating gene expression to create a peak of protein expression once every 24 hours to control when a particular physiological process is most active with respect to the solar day. Transcription and translation of core clock components (CLOCK, NPAS2, BMAL1, BMAL2, PER1, PER2, PER3, CRY1 and CRY2) plays a critical role in rhythm generation, whereas delays imposed by post-translational modifications (PTMs) are important for determining the period (tau) of the rhythms (tau refers to the period of a rhythm and is the length, in time, of one complete cycle). A diurnal rhythm is synchronized with the day/night cycle, while the ultradian and infradian rhythms have a period shorter and longer than 24 hours, respectively. Disruptions in the circadian rhythms contribute to the pathology of cardiovascular diseases, cancer, metabolic syndrome and aging. A transcription/translation feedback loop (TTFL) forms the core of the molecular circadian clock mechanism. Transcription factors, CLOCK or NPAS2 and BMAL1 or BMAL2, form the positive limb of the feedback loop, act in the form of a heterodimer and activate the transcription of core clock genes and clock-controlled genes (involved in key metabolic processes), harboring E-box elements (5'-CACGTG-3') within their promoters. The core clock genes: PER1/2/3 and CRY1/2 which are transcriptional repressors form the negative limb of the feedback loop and interact with the CLOCK|NPAS2-BMAL1|BMAL2 heterodimer inhibiting its activity and thereby negatively regulating their own expression. This heterodimer also activates nuclear receptors NR1D1/2 and RORA/B/G, which form a second feedback loop and which activate and repress BMAL1 transcription, respectively. PER1 and PER2 proteins transport CRY1 and CRY2 into the nucleus with appropriate circadian timing, but also contribute directly to repression of clock-controlled target genes through interaction with several classes of RNA-binding proteins, helicases and others transcriptional repressors. PER appears to regulate circadian control of transcription by at least three different modes. First, interacts directly with the CLOCK-BMAL1 at the tail end of the nascent transcript peak to recruit complexes containing the SIN3-HDAC that remodel chromatin to repress transcription. Second, brings H3K9 methyltransferases such as SUV39H1 and SUV39H2 to the E-box elements of the circadian target genes, like PER2 itself or PER1. The recruitment of each repressive modifier to the DNA seems to be very precisely temporally orchestrated by the large PER complex, the deacetylases acting before than the methyltransferases. Additionally, large PER complexes are also recruited to the target genes 3' termination site through interactions with RNA-binding proteins and helicases that may play a role in transcription termination to regulate transcription independently of CLOCK-BMAL1 interactions. Recruitment of large PER complexes to the elongating polymerase at PER and CRY termination sites inhibited SETX action, impeding RNA polymerase II release and thereby repressing transcriptional reinitiation. May propagate clock information to metabolic pathways via the interaction with nuclear receptors. Coactivator of PPARA and corepressor of NR1D1, binds rhythmically at the promoter of nuclear receptors target genes like BMAL1 or G6PC1. Directly and specifically represses PPARG proadipogenic activity by blocking PPARG recruitment to target promoters and thereby inhibiting transcriptional activation. Required for fatty acid and lipid metabolism, is involved as well in the regulation of circulating insulin levels. Plays an important role in the maintenance of cardiovascular functions through the regulation of NO and vasodilatatory prostaglandins production in aortas. Controls circadian glutamate uptake in synaptic vesicles through the regulation of VGLUT1 expression. May also be involved in the regulation of inflammatory processes. Represses the CLOCK-BMAL1 induced transcription of BHLHE40/DEC1 and ATF4. Negatively regulates the formation of the TIMELESS-CRY1 complex by competing with TIMELESS for binding to CRY1.
Synonyms: KIAA0347; FASPS; FASPS1
Tractability: Small molecule: a high-quality ligand is known. PROTAC: UniProt records ubiquitination sites on it; ubiquitination databases record sites on it; a small molecule that binds it is known.
Gene: Protein-coding gene on chromosome 2 (238,244,044 to 238,290,102, reverse strand). Ensembl gene ENSG00000132326.
Subcellular location: Nucleus (Isoform 1); Cytoplasm; Cytoplasm, perinuclear region; Nucleus, nucleolus (Isoform 2)
Subcellular location (Human Protein Atlas): Nucleoplasm; Cytosol
Pathways (Reactome):
Circadian clock: Degradation of CRY and PER proteins; Phosphorylated BMAL1:CLOCK (ARNTL:CLOCK) activates expression of core clock genes; Phosphorylation and nuclear translocation of the CRY:PER:kinase complex; Phosphorylation of CLOCK, acetylation of BMAL1 (ARNTL) at target gene promoters; The CRY:PER:kinase complex represses transactivation by the BMAL:CLOCK (ARNTL:CLOCK) complex
Gene Ontology:
Molecular function: protein binding; transcription cis-regulatory region binding; transcription coactivator activity; transcription corepressor binding
Biological process: chromatin remodeling; circadian regulation of gene expression; circadian rhythm; entrainment of circadian clock by photoperiod; fatty acid metabolic process; gluconeogenesis; glycogen biosynthetic process; lactate biosynthetic process; negative regulation of circadian rhythm; negative regulation of DNA-templated transcription; negative regulation of fat cell proliferation; negative regulation of protein ubiquitination; negative regulation of transcription by RNA polymerase II; positive regulation of cold-induced thermogenesis; regulation of cell cycle; regulation of circadian rhythm; regulation of glutamate uptake involved in transmission of nerve impulse; regulation of insulin secretion; regulation of neurogenesis; regulation of vasoconstriction; response to ischemia; white fat cell differentiation; neural retina development; positive regulation of DNA-templated transcription
Cellular component: nucleoplasm; nucleus; cytoplasm; cytosol; nucleolus; perinuclear region of cytoplasm
Genetic constraint (gnomAD): Loss-of-function variants: 54 observed, 101.09 expected, observed/expected ratio (o/e) 0.53, 90% interval 0.43 to 0.67. The upper end of that interval is the gene's LOEUF score, 0.67, which puts it in group 2 of 6, group 1 being the genes least tolerant of losing a copy. Missense variants: 1,380 observed, 1,516 expected, observed/expected ratio (o/e) 0.91, 90% interval 0.87 to 0.95. Synonymous variants: 618 observed, 625.48 expected, observed/expected ratio (o/e) 0.99, 90% interval 0.92 to 1.06.
Homologues: Orthologues: chimpanzee PER2 (99% identical), macaque PER2 (96% identical), mouse Per2 (79% identical), rat Per2 (78% identical), guinea pig PER2 (78% identical), pig PER2 (76% identical), dog PER2 (76% identical), rabbit PER2 (69% identical), zebrafish per2 (52% identical), tropical clawed frog per2 (50% identical), Drosophila melanogaster per (18% identical), Caenorhabditis elegans lin-42 (13% identical). Paralogues in human: PER1 (43% identical), PER3 (33% identical).
Diseases named in the same sentence as PER2 in open-access papers:
PER2 is named in the same sentence as 219 diseases in open-access papers, as found by Europe PMC text mining. Sharing a sentence is not in itself a finding about the gene and the disease. The quoted sentences say what the papers report.
breast cancer (69 papers, 2010 to 2025). A primary or metastatic malignant neoplasm involving the breast. "In terms of genetic predisposition, logistic regression analyses have linked different CLOCK, CRY1, and PER2 genotypes to breast cancer risk, and several studies have implicated specific single-nucleotide polymorphisms." (PMID 35163264, 2022). "This study shows that PER2 silencing increases the susceptibility of the chemoresistant MDA-MB-231 breast cancer cells to the cytotoxic effects of doxorubicin resulting in S phase arrest and induced apoptosis." (PMID 33114496, 2020). "Our analysis indicates that five SNPs, BMAL1 rs2279287, CLOCK rs12505266, CRY2 rs10838524, PER1 rs2735611, PER2 rs934945, are significantly associated with the breast cancer risk in the Polish association study." (PMID 31739444, 2019). "The patients having at least one or more risk alleles (among three significant SNPs CRY2 rs10838524; PER1 rs2735611; PER2 rs934945) were significantly associated with an increased breast cancer risk OR = 1.66 (1.17–2.35) p = 0.005." (PMID 31739444, 2019). "Potential significance of an increased predisposition to breast cancer was demonstrated for a recessive genetic model of PER2 rs11894491 OR = 1.53 (0.93–2.50) p = 0.09." (PMID 31739444, 2019). "In this line, polymorphisms affecting CLOCK (rs3805151), CRY1 (rs1056560), CRY2 (rs1401417), and PER2 (rs934945) have been associated to breast cancer risk in a Chinese population." (PMID 30873119, 2019). "Similar associations were observed between PER2 missense variant rs934945 under a dominant genetic model and an increased breast cancer risk OR = 1.56 (1.09–2.23), p = 0.01." (PMID 31739444, 2019). "The estrogen receptor-α (ERα) signaling pathway has been linked to the disruption of PER2 in breast cancer." (PMID 29780357, 2018). "Per genes are mutated or deleted in many tumor tissues, and altered PER2 expression is common in human breast cancer and in patients with prostate cancer." (PMID 28466226, 2017). "A recent study showed that POU2F1 regulates expression of the EMT genes Twist1, Snai1 and Snai2 under hypoxia-dependent loss of PER2 in breast cancer." (PMID 28489585, 2017). "In humans, Per2 expression is significantly reduced in both sporadic and familial primary breast cancers, and a few breast cancer cases contain PER2 mutations." (PMID 27036047, 2016). "In the group with three consecutive night shifts, the SNP rs11695472 in the PER2 gene (OR 2.69, 95% CI 1.08- 6.73) was associated with increased risk of breast cancer." (PMID 23822714, 2013). "Dysregulation or loss of PER1 and/or PER2 has been shown in human breast cancer tumor cells when compared with normal cells from adjacent tissue." (PMID 22076133, 2011). "Studies have reported that in breast cancer, the expression level of Znf704 is inversely associated with the expression level of Per2, and high levels of Znf704 are correlated with lymph node positivity, poor prognosis, and histological grading in patients with breast cancer." (PMID 38903177, 2024). "Low PER1 and PER2 expression is linked to breast cancer development and poorer outcomes." (PMID 35163264, 2022). "Another study showed that PER2 is associated with the development of breast cancer." (PMID 33633796, 2021). "Finally, simultaneous presence of CLOCK CC and PER2 AA genotypes resulted in a higher risk of developing breast cancer." (PMID 30873119, 2019). "Mutations in the Per2 gene, an essential regulator of the mammalian circadian clock system, have been identified in a wide range of human cancers, including colorectal and breast cancer." (PMID 27036047, 2016).
breast cancer (continued). "The Per2 gene is an essential regulator of the mammalian circadian clock system, and mutations arising in this gene have been identified in a wide range of human cancers including colorectal and breast cancer." (PMID 26347774, 2015). "Overexpression of PER2 in the MCF-7 breast cancer cell line leads to a notable increase in the proportion of cells in the G1 phase and a decrease in the S phase." (PMID 40243466, 2025). "In breast cancer patient samples, hypoxic conditions lead to PER2 degradation, supporting the general positive correlation between intratumoral PER2 and overall survival." (PMID 39463009, 2024). "In one study on the breast cancer cell line, Per2 silencing successfully sensitizes doxorubicin-resistant MDA-MB-231 breast cancer cells to its lethal effects." (PMID 35326729, 2022). "The expression levels of rhythm genes, such as CLOCK, PER1, PER2, PER3, CRY2, RORC and TIMELESS, are associated with the metastasis-free survival of breast cancer patients." (PMID 35180863, 2022). "For example, downregulation of the circadian gene PER2 increases Cyclin D and Cyclin E levels and consequently accelerates breast cancer growth." (PMID 35180863, 2022). "Per2 is known to have tumor suppressive activity against mammary tumors, and its down-regulation is advantageous for cancer progression." (PMID 33633796, 2021). "Consistent with our findings, there is compelling evidence for a mechanistic link between PER2 and the cell cycle, where the downregulation of PER2 accelerated the growth of breast cancer cells." (PMID 34943141, 2021). "In vitro studies showed that Per2 suppresses Esr1 transcription and induces Esr1 degradation and that Per2 is estrogen-inducible in Esr1 positive breast cancer cells." (PMID 32625167, 2020). "In breast epithelial cells, an altered estrogen receptor signaling has been related to breast cancer and two circadian clock genes, PER2 and ARNTL, both required for breast epithelial acinar morphogenesis in vitro." (PMID 30873119, 2019). "This case-control study analyzed the associations between breast cancer and polymorphisms in circadian clock genes (ARTNL, CLOCK, CRY2, NPAS, and PER2) and in genes of the melatonin pathway as well (AANAT and MTNR1B)." (PMID 30873119, 2019). "Only one SNP-rs11894491-showed a significant effect on a PER2 transcript level in mammary cancer-free tissues, based on the results from our dataset and the GTex eQTL calculator." (PMID 31739444, 2019). "Per1 is reduced in cancer tissue and its inhibition blunts apoptosis, whereas Per2 represses tumor in breast cancer and induces estradiol (E2) in mammary cells." (PMID 29607311, 2018). "Left - representative Per2::Luc traces from cultures of MECs isolated from the normal and tumour regions of patients with breast cancer." (PMID 30348208, 2018). "It was first reported in 2007 that suppression of PER2 leads to ERα stabilization, and conversely, overexpression of PER2 in breast cancer cells significantly inhibited cell growth and promoted apoptosis." (PMID 29780357, 2018). "Downregulation of Per1 and Per2 in rodent models initiates higher cancer cell growth, but on the other hand, overexpressed Per2 leads to apoptosis in mouse mammary carcinoma cell lines ETM6." (PMID 29958276, 2018). "rs2253820 in PER1 a synonymous G>A SNP had low level of evidence in breast cancer sub-group, as well as rs7602358 T>G downstream PER2." (PMID 28177907, 2017). "PER2 downregulation is present in leukemia, glioma, breast cancer; and its deletion results in the development of lymphomas." (PMID 27285754, 2016). "Per2 knockdown in U343 glioma cells promoted the tumor formation process in nude mice, which is consistent with gastric cancer and breast cancer research." (PMID 27036047, 2016). "This is consistent with in vitro and in vivo studies showing a deregulation of the G1/S transition after downregulation of Per2 in murine breast cancer cells, and cyclin D1-dependent cell cycle deregulation in Per2-/- mice models." (PMID 26741371, 2016).